MAP3K9-DT (MAP3K9 divergent transcript)
Synonyms: lincNMR
Gene: Long non-coding RNA gene on chromosome 14 (70,808,811 to 70,816,935, forward strand). Ensembl gene ENSG00000259153.
Diseases named in the same sentence as MAP3K9-DT in open-access papers:
MAP3K9-DT is named in the same sentence as 11 diseases in open-access papers, as found by Europe PMC text mining. Sharing a sentence is not in itself a finding about the gene and the disease.
MAP3K9-DT shares sentences with these, for which no sentence is quoted: tumor (7 papers); cancer (4); hepatocellular carcinoma (2); liver cancer (2); bladder urothelial carcinoma (1); breast carcinoma (1); breast invasive carcinoma (1); cervical squamous cell carcinoma (1); lung adenocarcinoma (1); lung carcinoma (1); lung squamous cell carcinoma (1).